BRCA1 (BRCA1 DNA repair associated)
Diseases named in the same sentence as BRCA1 in open-access papers (continued):
Sharing a sentence is not in itself a finding about the gene and the disease.
ovarian carcinoma (continued). "The germline BRCA1/2 pathogenic variants are widely reported among families with a strong history of breast/ovarian cancer, cohort of early‐onset BC patients, triple‐negative BC patients, pancreatic cancer patients, and among patients with prostate cancer." (PMID 35908255, 2023). "Previously, we reported a high prevalence of BRCA1/2 pathogenic variants (168/718; 23.4%), including 23 BRCA1 founder mutations in high-risk breast and/or ovarian cancer patients from Pakistan." (PMID 37951914, 2023). "In breast and ovarian cancer tumors with a known mutation in HR genes, such as BRCA1 or BRCA2, a higher tumor mutational burden and a greater number of tumor-infiltrating lymphocytes have been observed; however, this outcome did not occur in our cohort." (PMID 37761329, 2023). "The BRCA1 and BRCA2 tumor suppressor genes are critical for the HRR of DNA double‐strand breaks by the HRR pathway; therefore, BRCA1/BRCA2‐mutated ovarian cancers are usually more sensitive to cisplatin." (PMID 37229486, 2023). "We employed the ovarian cancer cell line UWB1.289 that presents a pathogenic frameshift mutation in BRCA1 and an HRD score of 67 as a control to evaluate the drug response of the HRDhigh sarcoma models." (PMID 36779660, 2023). "BRCA1 also acts as a tumor suppressor gene, which is frequently mutated in familial breast and ovarian cancers." (PMID 37656691, 2023). "BRCA1-mutated patients have a lifetime risk of developing BC of 65% and an ovarian cancer risk of 39%, while the risk of BC is 45% and the risk of ovarian cancer is 17% in BRCA2-mutated patients." (PMID 37109459, 2023). "This operation has been shown to lower the likelihood of developing ovarian cancer by 96% and the risk of breast cancer by 53% in individuals who have the BRCA1 or BRCA2 mutation." (PMID 37370973, 2023). "BRCA1 somatic variants were common in breast and ovarian cancers but occurred less frequently than germline variants." (PMID 37916805, 2023). "Deregulated expression of the BRCA1 increases the amount of 5′ extended transcript and causes a decrease in the BRCA1 protein noticed in breast and ovarian cancers." (PMID 36769304, 2023). "Other non-BRCA1/2 genes associated with breast and/or ovarian cancer (in less than 6% of hereditary cases), are targeted by NGS-based multigene panel diagnostics adopted for affected families, which is not the focus of this report." (PMID 37400873, 2023). "The objective of our study was to explore the potential of using a polygenic risk score (PRS) to estimate the overall genetic risk of developing breast or ovarian cancer for women with inherited BRCA1 pathogenic variants." (PMID 37296919, 2023). "The reported germline BRCA1/2 mutations in Chinese patients with hereditary breast and ovarian cancer are highly ethnically specific." (PMID 38068930, 2023). "When treating platinum-sensitive relapse ovarian cancer cells with germline BRCA1/2 mutations, Fluzoparib also exhibited good safety and antitumor activity profiles." (PMID 37351512, 2023). "Olaparib treatment was associated with an activated effector T-cell response and reduction of immune-checkpoint receptor expression in in vivo models of BRCA1-deficient ovarian cancer." (PMID 36978917, 2023).
ovarian carcinoma (continued). "Several genes have been associated with increased risk of ovarian cancer, including BRCA1 and BRCA2, PALB2, BRIP1, RAD51C and RAD51D, with the largest percentage of cases (10-15%) being attributable to germline pathogenic variants in BRCA1 or BRCA2." (PMID 37076566, 2023). "The loss of BRCA1 in ovarian cancer decreased the rate of fatty acid oxidation and increased the expression of NADPH and Myc." (PMID 37110218, 2023). "While BRCA1/2 mutations are strong biomarkers for predicting benefit from PARPi in patients with epithelial ovarian cancer, they cannot accurately identify all patients who will benefit from these agents." (PMID 38067228, 2023). "This appeared to be due to later ovarian cancer onset in carriers of BRCA2 mutations compared with their BRCA1 counterparts, after childbearing age." (PMID 37664647, 2023). "Previously, we reported 23.4% prevalence of BRCA1/2 pathogenic variants among Pakistani high-risk breast and/or ovarian cancer families." (PMID 37951914, 2023). "Here, we report for the first time the multiple ascertainment of the BRCA1 pathogenic missense variant c.5207T > C; p.Val1736Ala (V1736A) rs45553935 as part of routine clinical care in breast and ovarian cancer families from Orkney." (PMID 36927983, 2023). "A multicenter case–control study of the Australian Ovarian Cancer Study Group found that germline BRCA1/2 mutation was an independent predictor of improved OS and PFS." (PMID 37174000, 2023). "The ARIEL4 Phase III clinical trial was a randomized, controlled, open-label study that sought to evaluate the efficacy of rucaparib as an alternative treatment option to chemotherapy for patients with relapsed, BRCA1/2-mutated ovarian cancers." (PMID 37035242, 2023). "It has been shown that around 10–15% of epithelial ovarian cancer (EOC) patients carry germline mutation in BRCA1 or BRCA2 with the highest incidence seen with HGSE subtypes." (PMID 37181681, 2023). "Ovarian cancer was the second and third most common cancer among female relatives of BRCA1 (21.95-fold increased risk) and BRCA2 carriers (4.65-fold increased risk), respectively." (PMID 36861435, 2023). "Women who have inherited the pathogenic BRCA1 variant tend to suffer from ovarian cancer at a younger age." (PMID 37746296, 2023). "The search for “BRCA3” has led to the conclusion that no gene with a similar population frequency of pathogenic variants and associated breast and ovarian cancer risk as BRCA1 or BRCA2 exists." (PMID 37563628, 2023). "AC004943.2 was identified as one of three lncRNAs to be associated with BRCA1/2 that enabled prognosis prediction as well as prediction of response to chemotherapy in patients with ovarian cancer." (PMID 37182169, 2023). "Other genes with a notable hysterectomy risk (at p < 1e−9) were MSH6 (OR = 3.3; p = 1.9e−20) and BRCA1 (OR = 1.9; p = 9.5e−10), most likely explained by susceptibility to endometrial and ovarian cancers, respectively." (PMID 36773604, 2023). "PARP inhibitors were approved by the FDA in advanced ovarian cancer and metastatic breast cancer with germline BRCA1/2 mutations." (PMID 37345194, 2023). "Patients with inherited BRCA gene alterations have an increased risk of ovarian cancer, exceeding 5% in the early 40s for BRCA1 carriers and in the early 50s for BRCA2 carriers." (PMID 37917945, 2023). "Borderline tumours, a separate entity of non-invasive epithelial ovarian cancers, are also characterised by a low frequency of BRCA1 and BRCA2 germline pathogenic variants." (PMID 37076566, 2023). "Around 14% of epithelial ovarian cancers are due to BRCA1 and BRCA2 mutations, and about 65–85% of inherited ovarian tumors have resulted from a mutation in the BRCA germline." (PMID 36376606, 2023). "Approximately 11–15% of ovarian cancer patients have BRCA1/2 germline mutations, 7% have BRCA1/2 somatic mutations, and it has been reported that HRD is found in about 50% of patients with epithelial ovarian cancer." (PMID 37370704, 2023).
ovarian carcinoma (continued). "Schaefer and Serrano’s seminal work established a framework for correlating gene mutations with specific tissues, showcased through their analysis of BRCA1—a pivotal gene associated with hereditary breast and ovarian cancer." (PMID 37762577, 2023). "Whereas, the frequency of the BRCA1 c.4096+1G>A variant on total number of individuals screened because of a personal and/or familial breast/ovarian cancer history is 0.97% (38/3803)." (PMID 37958491, 2023). "Approximately 18% of epithelial ovarian cancer cases, particularly high-grade serous carcinomas, are due to inherited mutations in BRCA1/2 genes; these mutations account for almost 40% of ovarian cancer cases in women with a family history of the disease." (PMID 37035242, 2023). "Risk-reducing bilateral salpingo-oophorectomy (RRBSO) is the gold standard for the prevention of ovarian cancer with an 80–96% risk reduction in patients with BRCA1/2 GPVs." (PMID 37258796, 2023). "BRCA1 participates in the DNA damage response and mutations in BRCA1 are associated with a high risk of breast and ovarian cancer." (PMID 37143582, 2023). "This new paradigm of ovarian cancer genesis was based on the original observation of dysplastic epithelium in the fallopian tube in women carrying BRCA1 and BRCA2 germline mutations." (PMID 37853473, 2023). "Rucaparib was approved for advanced BRCA1/2 mutated ovarian carcinomas following multiple chemotherapy treatments, while niraparib was approved for homologous recombination deficiency (HRD)-positive gynecological cancers." (PMID 37035242, 2023). "Strong family history of breast and ovarian cancer indicates high likelihood of germline BRCA1 or BRCA2 pathogenic variant." (PMID 37173335, 2023). "Consistently, in ovarian cancer, patients with biallelic BRCA1/2 mutations showed improved outcomes than those with monoallelic BRCA1/2 mutations." (PMID 37765210, 2023). "It is today essential that every patient with newly diagnosed high grade ovarian cancer is offered testing for BRCA1/2 gene pathogenic variant and genomic instability." (PMID 37932736, 2023). "An inherited single nucleotide variant (SNV) in the 5′UTR of the BRCA1 gene c.-107A > T was identified to be related to BRCA1 promoter hypermethylation and a hereditary breast and ovarian cancer phenotype in two UK families." (PMID 36112334, 2023). "In the case of the breast and ovarian cancer specific tumor suppressor protein, BRCA1, pathogenic missense variants frequently score as loss of function in an assay for homology-directed repair (HDR) of DNA double-strand breaks." (PMID 37090572, 2023). "The life-time risk for developing ovarian cancer in individuals harboring BRCA1 mutations is 39–48%, compared with 11–20% in those harboring BRCA2 mutations." (PMID 37664647, 2023). "The corresponding ovarian cancer risks was found to be 44% for BRCA1 and 17% for BRCA2 mutation carriers." (PMID 36647026, 2023). "Mutations in BRCA1, a tumor suppressor gene, have been linked to heightened breast and ovarian cancer risks." (PMID 37762577, 2023). "The UK Collaborative Trial of Ovarian Cancer Screening highlights the importance of surveillance for BRCA1/2 mutation carriers based on transvaginal ultrasound and CA-125 starting at 30 years of age." (PMID 37519818, 2023). "Identifying germline BRCA1/2 mutation carriers is vital for reducing their risk of breast and ovarian cancer." (PMID 37291133, 2023). "Women who carry an inherited deleterious mutation in the BRCA1 or BRCA2 gene face the highest risk of developing ovarian cancer." (PMID 38136256, 2023). "RAD51C mutations have previously been reported to increase the risk for breast and ovarian cancer and to also be causative for a recessively inherited Fanconi anemia-like disorder, similar to BRCA1, BRCA2 and PALB2 mutations." (PMID 37578974, 2023). "•The ESMO guidelines state that all patients with high-grade ovarian cancer should be tested for BRCA1 and BRCA2 mutations (germline/somatic) at diagnosis." (PMID 37181681, 2023).
ovarian carcinoma (continued). "The alteration in one of the other HRR factors led to cells that show features like that of the BRCA1/2 mutation carrier: this status, defined as “BRCAness”, is also related to a greater risk of developing breast and ovarian cancer." (PMID 38069422, 2023). "PARP inhibitor treatment is recommended for maintenance therapy for stage II-IV disease or persistent or recurrent disease in BRCA1/2 mutated ovarian cancer." (PMID 37664050, 2023). "Of those diagnosed with ovarian cancer, 15% were found to harbor germline mutations in BRCA1 or BRCA2." (PMID 37958491, 2023). "Ovarian cancer histological subtypes were assessed for their potential utility in future prediction of germline BRCA1 or BRCA2 variant pathogenicity." (PMID 37076566, 2023). "These inhibitors have been approved for the treatment of breast and ovarian cancers with BRCA1/2 mutations." (PMID 38111536, 2023). "Approximately 20–30% of epithelial ovarian cancers occur in females with an inherited predisposition; most of these hereditary ovarian cancers are due to germline mutations in BRCA1 and BRCA2 genes." (PMID 37143950, 2023). "Although pharmacological ablation is widely believed to be at least as effective as surgical ablation, surgery is primarily used in a risk-reduction setting for women with an increased risk of both breast and ovarian cancer due to BRCA1 or BRCA2 mutations." (PMID 36835955, 2023). "Mutations in breast- and ovarian-cancer-predisposing genes BRCA1 and, especially, BRCA2 are also associated with increased risk for pancreatic cancer development." (PMID 36975505, 2023). "Constitutional BRCA1 promoter methylation has been shown to potentially correlate with the risk of ovarian cancer." (PMID 37434214, 2023). "Increased IFNγ and TNFα production by CD8 T cells and NK cells was also observed in a BRCA1-deficient ovarian cancer model upon treatment with PARPis." (PMID 36831435, 2023). "BRCA1 mutations have been associated with breast and ovarian cancers, as well as prostate, pancreas, gastric, and colorectal cancers." (PMID 37958970, 2023). "The ovarian cancer surveillance for BRCA1/2 mutation carriers recommend the evaluation of CA-125 level in combination with transvaginal ultrasound starting at 30 years of age." (PMID 37519818, 2023). "In summary, these findings do not support a strong association between early-life physical activity and ovarian cancer among women with a BRCA1 or BRCA2 mutation." (PMID 38019076, 2023). "The response of the HRDhigh sarcoma models to WEE1 inhibition was comparable with the BRCA1‐mutated ovarian carcinoma cells." (PMID 36779660, 2023). "Ovarian cancer screening in BRCA1/2 mutation carriers utilizes assessment of carbohydrate antigen 125 (CA125) and transvaginal ultrasound (TVU), despite low sensitivity and specificity." (PMID 37393265, 2023). "We report the concordance between germline and tumour BRCA1/2 pathogenic variants in a large, real-world cohort of patients diagnosed with epithelial ovarian cancer." (PMID 38201604, 2023). "Herein, we investigated the synergism of PSPC1 inhibition in combination with olaparib in a preclinical model with PSPC1-expressing, BRCA1/2-mutated breast and ovarian cancer, demonstrating the synergistic anticancer activity of the combination." (PMID 38069409, 2023). "Consistently, carriers of BRCA1 loss of function mutations have a lifetime risk of 70–80% for breast and 44% for ovarian cancer." (PMID 36614323, 2023). "Of these, half of the P/LP variants identified in patients with breast or ovarian cancer were in genes other than BRCA1/2." (PMID 37174101, 2023). "Here, we investigated the ability of paraspeckle component 1 (PSPC1), as an additional synthetic lethal partner with BRCA1/2, to enhance olaparib sensitivity in preclinical models of BRCA1/2-mutated breast and ovarian cancers." (PMID 38069409, 2023).
ovarian carcinoma (continued). "For ovarian cancer, women with BRCA1 PV have a cumulative lifetime risk of 44 % (95% CI 36–53), whereas BRCA2 PV carriers carry a risk of 17% (95% CI 11–25)." (PMID 36767056, 2023). "The question of why a gene such as BRCA1, which is required for DNA damage repair and proper DNA replication in all cells, increases the risk of breast and ovarian cancers has been opened to debate." (PMID 37509303, 2023). "For the 759 patients with a personal and/or familial history of only ovarian cancer, as expected, BRCA1/2 genes were the most frequently mutated, followed by RAD51C and RAD51D." (PMID 37444530, 2023). "The primary outcome is the cumulative tubo-ovarian cancer incidence at the target age: 46 years for BRCA1 and 51 years for BRCA2 pathogenic variant carriers." (PMID 37045546, 2023). "Breast cancer 1 gene (BRCA1) is one of the most implicated genes in hereditary breast and ovarian cancers." (PMID 37474724, 2023). "For example, phase 2 trials are ongoing (NCT00753545) using PARP inhibitor Olaparib in patients with ovarian cancer that recurred within 12 months of prior platinum therapy, with confirmed germline BRCA1/BRCA2 mutation." (PMID 36829496, 2023). "PARP inhibitors (PARPi) that inhibit PARP catalytic activity and induce PARP trapping are commonly used for treating BRCA1/2-deficient breast and ovarian cancers through synergistic lethality." (PMID 36909172, 2023). "Approximately 10–15% of patients with epithelial ovarian cancer have an inherited (germline) BRCA1 or BRCA2 mutation." (PMID 38201604, 2023). "This concept is already exploited clinically in familial breast and ovarian cancer, where patients often harbor a heterozygous BRCA1/2 germline mutation and develop cancer after a somatic loss of the second allele." (PMID 38139386, 2023). "Strikingly, our data suggest PRT543 potently inhibits olaparib-resistant ovarian cancer cell line models with endogenous BRCA1 mutation that have been engineered to re-express BRCA1, as well as long-term drug-induced acquired resistance to olaparib." (PMID 37861290, 2023). "For example, somatic changes in methylation at the BRCA1 promoter, result in reduced expression of BRCA1, homologous DNA repair deficiency and shorter survival in primary ovarian cancers." (PMID 35883104, 2022). "Overall, our results from RNA-seq and IHC suggest that PARP1 is highly expressed in BRCA1/2 mutation-associated breast and ovarian cancers." (PMID 36344544, 2022). "It should be taken into account that these BRCA1 founder mutations carriers were thus protected against ovarian cancer, and therefore, we observe their lower representation among BRCA1/2 mutation carriers who have now developed ovarian cancer." (PMID 35382848, 2022). "Nonsense mutations in BRCA1 lead to inactive truncated protein products and are associated with high risk of breast and ovarian cancer." (PMID 35837282, 2022). "In fact, in the ARIEL2 trial of the PARP inhibitor rucaparib in ovarian cancer, tumor biopsies revealed positive associations between alterations in BRCA1 or RAD51C, high genomic loss of heterozygosity (gLOH), and increased response to rucaparib." (PMID 35626165, 2022). "The most frequent variant in BRCA1 was c.5470_5477del (p.I1824Dfs*3, n = 3), which was considered a founder variant in the Chinese Han patients with BC or ovarian cancer." (PMID 36232564, 2022). "The estimated lifetime risk of developing ovarian cancer is 25%–65% and 15%–20% in patients with BRCA1 and BRCA2 mutations, respectively." (PMID 36531159, 2022). "One clinical trial (SOLO2/ENGOT-Ov21) demonstrated that olaparib provided a median OS benefit of 12.9 months compared with placebo in patients with platinum-sensitive, relapsed ovarian cancer and a BRCA1/2 mutation." (PMID 35186166, 2022).